KRTAP10-8 (keratin associated protein 10-8)
Description:
In the hair cortex, hair keratin intermediate filaments are embedded in an interfilamentous matrix, consisting of hair keratin-associated proteins (KRTAP), which are essential for the formation of a rigid and resistant hair shaft through their extensive disulfide bond cross-linking with abundant cysteine residues of hair keratins. The matrix proteins include the high-sulfur and high-glycine-tyrosine keratins.
Synonyms: KAP10.8; KRTAP18-8; KRTAP18.8
Tractability: No criterion of Open Targets' tractability assessment is met for any kind of drug.
Gene: Protein-coding gene on chromosome 21 (44,612,079 to 44,612,954, forward strand). Ensembl gene ENSG00000187766.
Pathways (Reactome):
Developmental Biology: Keratinization
Gene Ontology:
Molecular function: identical protein binding; protein binding
Cellular component: cytosol; keratin filament
Genetic constraint (gnomAD): Loss-of-function variants: 1 observed, 0.8 expected, observed/expected ratio (o/e) 1.25, 90% interval 0.29 to 1.91. That is too few expected variants to judge how well the gene tolerates losing a copy. Missense variants: 323 observed, 336.57 expected, observed/expected ratio (o/e) 0.96, 90% interval 0.88 to 1.05. Synonymous variants: 153 observed, 144.34 expected, observed/expected ratio (o/e) 1.06, 90% interval 0.93 to 1.21.
Homologues: Orthologues: chimpanzee KRTAP10-8 (97% identical), macaque KRTAP10-8 (88% identical). Paralogues in human: KRTAP10-12 (72% identical), KRTAP10-11 (70% identical), KRTAP10-7 (69% identical), KRTAP10-9 (69% identical), KRTAP10-4 (69% identical), KRTAP10-5 (66% identical), KRTAP10-6 (66% identical), KRTAP10-10 (63% identical), KRTAP10-1 (61% identical), KRTAP10-3 (60% identical), KRTAP10-2 (59% identical), KRTAP16-1 (34% identical), and 35 more.